CYP3A4 (cytochrome P450 family 3 subfamily A member 4)
Diseases named in the same sentence as CYP3A4 in open-access papers (continued):
Sharing a sentence is not in itself a finding about the gene and the disease.
colorectal cancer (18 papers, 2002 to 2025). A primary or metastatic malignant neoplasm that affects the colon or rectum. "Elevated expression of CYP3A4 in colorectal cancer patients can result in the greater metabolism of drugs that are metabolized by this enzyme, leading to rapid clearance of the drugs from the body." (PMID 37568755, 2023). "Expression analysis of prototypical PXR target genes ABCB1 and CYP3A4 in LS174T colorectal cancer cells and HepaRG hepatocytes revealed novel antagonists as selective receptor modulators, which showed gene- and tissue-specific effects." (PMID 35455978, 2022). "In T84 cells, which are derived from human colorectal carcinoma and thought to be a potential alternative to Caco-2 cells, the expression of CYP3A4 is controversial, while expressions of CYP2B6, CYP2C9, CYP2C19, and CYP2E1 are lacking." (PMID 34604364, 2021). "This study is aimed to assess the potential of CYP3A activity in colorectal cancer as a putative resistance mechanism capable to influence anticancer therapy with drugs that are CYP3A4 substrates." (PMID 12237780, 2002). "Major clinical implications of the putative presence of CYP3A in colorectal epithelium derive from the use of anticancer drugs that are CYP3A4 substrates in colorectal cancer therapy." (PMID 12237780, 2002). "This study provides novel information on several relevant issues, including the demonstration of the presence in colorectal cancer cells of a constitutive enzyme that permits the inactivation of CYP3A4 substrates." (PMID 12237780, 2002). "Therefore, the aim of this study was to extensively investigate the association between genetic polymorphisms in CYP3A4/5, DPYD, UGT1A1, ABCB1, ABCC2, and ABCG2 and irinotecan induced-toxicity in cohort of Thai colorectal cancer patient." (PMID 32778670, 2020). "However the interaction of CYP3A4 and CYP3A5 gene polymorphisms and the risk of developing the major digestive cancers such as liver, stomach or colorectal cancers remain unexplored." (PMID 17605821, 2007). "The main paclitaxel metabolite in colorectal cancer is 3′-p-hydroxypaclitaxel, a CYP3A4 metabolite." (PMID 12237780, 2002). "Therefore the presence of CYP3A4 enzyme activity in colorectal cancer cells may also influence tumour sensitivity to these drugs." (PMID 12237780, 2002). "For instance, fisetin controls miR-3664-3p expression in HCT116 cells, thereby decreasing drug resistance of colorectal cancer cells by targeting ABCG2, CYP3A4, MCL1, and MLH1." (PMID 41470858, 2025). "Both CYP3A4 and CYP3A5 are expressed in liver, stomach, colorectal epithelium and in colorectal cancer tissue, although large interindividual differences exist in the expression of both enzymes." (PMID 17605821, 2007). "Evidences indicating the presence of CYP3A4 and CYP3A5 mRNA transcripts in human colorectal epithelium and in cultured colorectal cancer lines have been reported." (PMID 12237780, 2002). "Moreover, studies involving drug-metabolizing enzyme activity have investigated enzymes like CYP3A4/5, CYP3A4, CYP3A, and CYP2D6 and diseases, including colorectal cancer, depression, lymphoid malignances, and so on." (PMID 34867363, 2021). "Thus, the aim of this study was to assess the allele and genotype frequencies and the relationship between CYP3A4/5, DPYD, UGT1A1, ABCB1, and ABCC2 genetic variations and irinotecan-induced toxicity in Thai colorectal cancer patients." (PMID 32778670, 2020). "Additionally, it was also shown that human colorectal cancer cells are able to inactivate the anticancer drug paclitaxel through metabolism by CYP2C8 and CYP3A4, demonstrating an example of acquired therapeutic resistance through induction of DXME37." (PMID 28684774, 2017). "Moreover, a lower level of PXR promoter methylation was observed in colorectal cancer tissues compared with adjacent normal mucosa, suggesting upregulation of the PXR/CYP3A4 mRNAs during carcinogenesis." (PMID 21342487, 2011).
colorectal cancer (continued). "CYP3A4 and CYP3A5 genotypes in colorectal cancer patients according tumor site." (PMID 17605821, 2007). "The novel antagonists 73 and 100 demonstrated gene-specific effects in LS174T colorectal cancer cells, not inducing on their own the expression of ABCB1, but inducing CYP3A4 expression to a similar extent as rifampicin." (PMID 35455978, 2022).
fungal infections (17 papers, 2020 to 2025). "Azole antifungals are used for prevention of fungal infections in at risk patients, but are also known inhibitors of CYP3A4." (PMID 34250757, 2022). "Further studies are needed to determine whether the metabolism of ATO is associated with CYP3A4 or P-gp when patients receive treatment for fungal infections combined with dyslipidemia pharmacotherapy and whether VOR could affect the efficacy and safety of ATO in clinical practice." (PMID 37251310, 2023). "Ruxolitinib is primarily metabolized by the cytochrome P450 (CYP450) enzymes, specifically CYP2C9 and CYP3A4.31,32 Azoles are potent CYP3A4 inhibitors and commonly used for prophylaxis or treatment of fungal infections during aGVHD treatment." (PMID 39438467, 2024). "Patients who experienced grade 3/4 infectious complications were fewer among the CYP3A4-interactions group, accordingly with shorter neutropenia and with prevention of fungal infections." (PMID 37051529, 2023). "Posaconazole, which is used to prevent invasive fungal infections, also functions as a potent inhibitor of CYP3A4." (PMID 37274294, 2023). "As patients with GvHD have an increased risk of invasive fungal infections, RUX is frequently combined with posaconazole (POS), a strong CYP3A4 inhibitor." (PMID 36559050, 2022). "In this study, we investigated the association of SNPs in CYP2C19, CYP3A4, ABCB1, and FMO3 and the plasma concentrations of voriconazole in Thai patients with invasive fungal infections." (PMID 33124772, 2020). "Fluconazole, for example, which is used to protect preterm infants from fungal infections, is an inhibitor of CYP3A4 and will decrease the clearance of doxapram that is mainly metabolized by this enzyme." (PMID 32477133, 2020). "Two of our patients developed fungal infections during anti-leukemic treatment with venetoclax, a CYP3A4 substrate; thus, azoles were not administered to avoid venetoclax dose reductions due to potential drug–drug interactions." (PMID 35628696, 2022). "Therefore, it is crucial to focus on the impact of CYP2C19, CYP3A4, and CYP2C9 gene phenotypes in hepatic insufficiency patients on VRZ plasma concentrations, as this holds positive implications for the successful treatment of hepatic insufficiency with concomitant invasive fungal infections." (PMID 37693307, 2023). "Once daily dosing, a favorable drug-drug interaction profile with no significant CYP3A4 inhibition, and wide tissue distribution contribute to the positioning of FMGX for empiric, front-line therapy for the treatment of invasive fungal infections." (PMID 33105672, 2020).
neutropenia (17 papers, 2014 to 2026). A decrease in the number of neutrophils found in the blood. "The cause of prolonged neutropenia was considered to be the drug interaction between venetoclax and azoles, which are moderate-to-strong CYP3A4 inhibitors, and high serum venetoclax levels have been reported in Asian subjects." (PMID 36530436, 2022). "Neutropenia and uveitis have previously been identified as severe adverse events associated with the co-administration of rifabutin with a CYP3A4 inhibitor." (PMID 25406657, 2014). "Clozapine pharmacokinetics is influenced by CYP3A4 and CYP3A5 activity, as well as polymorphisms in HLA-B that can cause clozapine-induced neutropenia." (PMID 35722694, 2022). "The FDA package insert for ruxolitinib warns against the concomitant use of CYP3A4 inhibitors during treatment of GVHD, myelofibrosis, and polycythemia vera (PCV), which may cause neutropenia and thrombocytopenia." (PMID 41528615, 2026). "In addition, a reduced dose of ruxolitinib (5 mg BID) is recommended when patients have severe cytopenia, thrombocytopenia, neutropenia, or elevated total bilirubin, or when administered with strong CYP3A4 inhibitors." (PMID 38361117, 2024). "This aligns with the most recent European Conference on Infections in Leukaemia (ECIL)-10 guidelines, which recommend mold-active prophylaxis for AML patients experiencing prolonged neutropenia and mandate VEN dose adjustment when combined with moderate or strong CYP3A4 inhibitors." (PMID 40807220, 2025). "The duration of neutropenia appears not to be affected by concomitant treatment with CYP3A4 inhibitors (mostly antifungals), in contrast to platelet recovery, which seems to be influenced by concomitant CYP3A4 inhibitor treatment." (PMID 40725703, 2025). "Duration of neutropenia trended to lower values among patients receiving CYP3A4–inhibitors than among patients who did not (median 34.5 days vs 20.5, respectively; p 0.19), as well as duration of thrombocytopenia (median 17 days vs 21.5 days, respectively; p 0.923)." (PMID 37051529, 2023). "Here, we evaluated additional SNPs on the candidate genes: CYP3A4*22, GSTP1, ERCC2, SLCO1B1, and ABCG2, but did not observe a significant relationship with neutropenia and neurotoxicity except for XRCC3 316A>G rs1799794 for GG+AG alleles (p = 0.03)." (PMID 29163177, 2017).
cardiac arrhythmia (16 papers, 2006 to 2024). Any disturbances of the normal rhythmic beating of the heart or MYOCARDIAL CONTRACTION. "Terfenadine can cause cardiac arrhythmias when used in combination with drugs that inhibit CYP3A4 activity." (PMID 39715174, 2024). "Nifedipine and tamsulosin are substrates of CYP3A4 and inhibition by ritonavir can cause potential hypotension and cardiac arrhythmias." (PMID 28044114, 2016). "In both cases, fluconazole can decrease the CYP3A4 metabolism of amitriptyline and methadone and increase the serum concentration with a higher risk of causing drugs-related adverse effects, such as arrhythmias or QT interval prolongation." (PMID 26068584, 2015). "Co-prescription of CYP3A4-inhibitors with calcium-channel blockers increases the risk of hypotension and acute kidney injury, which may further induce hyperkalemia and arrhythmia." (PMID 33971831, 2021). "Existing evidence suggests that the individual risk of cardiac arrhythmias secondary to these antimicrobials is minimal; yet, when combined with a genetic propensity to poor metabolism of CYP3A4-inducing medications and co-administration with other CYP potentiators, the risk may be magnified." (PMID 29790845, 2018). "Amiodarone is a drug used in the treatment of cardiac arrhythmias, which is metabolized to mono-N-desethylamiodarone and di-N-desethylamiodarone by CYP3A4, and can become toxic upon CYP3A4 induction." (PMID 31676845, 2019).
depression (15 papers, 2014 to 2024). "This is the first study of CYP3A4*1B polymorphism performed on a group of people suffering from depression." (PMID 31025537, 2019). "It is possible that there is a link between the occurrence of depression and the genotype containing the CYP3A4*1B mutant allele." (PMID 31025537, 2019). "Vilazodone, commonly used to treat major depressive disorder in adults, is metabolized mainly by the hepatic CYP3A4 enzyme system and one of the major inactive metabolites of vilazodone is M10." (PMID 38702755, 2024). "Aripiprazole, a third-generation antipsychotic drug, is extensively metabolized by CYP2D6 and CYP3A4 isoenzymes, while bupropion, used in depressive disorders, is known as a moderate or strong CYP2D6 enzyme inhibitor." (PMID 39590825, 2024). "The pharmacogenetic variable “reduced metabolism of quetiapine”, based on the analysis of the CYP3A4*22 allele, was associated with lower scores in the CGI-BP-M overall and depression subscales, thus positively impacting the likelihood of response." (PMID 34440433, 2021). "The variable “reduced metabolism of quetiapine”—determined by the presence of CYP3A4*22 allele—was identified as a significant predictor of lower scores in the overall CGI-BP-M (p-value < 0.038) and the depression subdomain (p-value < 0.025) at enrollment." (PMID 34440433, 2021). "This work shows that CSS specifically increases CYP3A4 translation via the nuclear receptor PXR in LQS of depression." (PMID 31781287, 2019). "The sophisticated compounds of CSS make it difficult to elucidate the therapeutic mechanisms of CYP3A4 regulation following depression." (PMID 31781287, 2019). "The activity of CYP3A4 which was the main metabolic enzyme of Sax had significantly increased in the depression group rats, which accelerated the metabolic rate of Sax." (PMID 26819853, 2016). "On the contrary, the four other gene variants analyzed (CYP3A4 rs2242480, CYP3A4 rs35599367, CNR17B rs1049353, and FAAH rs2295632) as other variables (other drugs and painkillers taken, depression, and anxiety conditions) remained very far from being significant." (PMID 37509416, 2023). "Although we confirmed that CSS increases CYP3A4 expression via the pregnane X receptor in the LQS of depression mouse model, the mechanisms of CSS in depressive patients remain unclear due to species differences between rodents and humans." (PMID 31781287, 2019). "The study suggests that CYP3A4*1B polymorphism have no influence on the predisposition to depression, the severity of depressive symptoms and the efficiency of antidepressant therapy." (PMID 31025537, 2019). "In the PPI network, DPP4, CYP3A4, EP300 MGAM and NR1H4 showed higher degrees and were identified as essential genes of intestinal microbiota influencing the occurrence of depression through the brain–gut axis." (PMID 37433869, 2023). "In conclusion, the intestinal microbiota can affect the development of depression through the metabolites equol, genistein and quercetin, which act on the critical targets of DPP4, CYP3A4, EP300, MGAM and NR1H4." (PMID 37433869, 2023). "Cyclobenzaprine, a medication that creates a high anticholinergic burden, can exacerbate depression, and could be contributing to CYP1A2, CYP2D6, and CYP3A4 overload." (PMID 34063850, 2021). "Probably the analysis for CYP3A4*1B were performed for the first time in the group of patients suffering from depression, therefore it is not possible to compare them with other data." (PMID 31025537, 2019). "We found that CSS ameliorated the depression-like symptoms and upregulated the CYP3A4 protein in LQS but not in LSSD, suggesting that CYP3A4 could be responsible for the syndrome-specific effects of CSS on LQS-mediated depression." (PMID 31781287, 2019).
dyslipidemia (15 papers, 2007 to 2025). "Liver function and dyslipidemia of participants with drinking histories were compared between CYP3A4*1G mutation (GA+AA) and wild-type (GG) groups." (PMID 38117809, 2023). "On the other hand, a study of > 950,000 patient records from US databases showed that 83% of patients with dyslipidemia used a CYP3A4-metabolised statin and that, of these, 25%-30% also received a CYP3A4 inhibitor." (PMID 28177908, 2017). "An example of a drug–drug interaction that increases the risk of adverse events comes from the United States of America where 83 % of patients with dyslipidemia is treated with a CYP3A4-metabolized statin of whom 25–30 % concomitantly use a CYP3A4-inhibitor." (PMID 27554244, 2017). "Lovastatin is a prescription drug frequently used to treat dyslipidemia and cardiovascular diseases and it is a specific substrate for CYP3A4 in the liver." (PMID 27322236, 2016). "A study of >950,000 patient records from two US databases showed that 83% of patients with dyslipidemia used a CYP3A4-metabolized statin and that, of these, 25 to 30% also received a CYP3A4 inhibitor." (PMID 23819752, 2013). "In sub-group of participants with alcohol drinking, liver injury and dyslipidemia has no statistical significance between CYP3A4*1G mutation and wild-type group." (PMID 38117809, 2023). "The lack of requirement of CYP3A4 metabolism for rosuvastatin makes it an attractive lipid-lowering drug to treat the dyslipidemia associated with HAART." (PMID 17958912, 2007). "Computational analyses and cell-free biochemical assays predicted a weak to moderate inhibitory activity of clinically relevant concentrations of silibinin against CYP3A4 when compared with recommended (rosuvastatin) and non-recommended (simvastatin) statins for lorlatinib-associated dyslipidemia." (PMID 36077379, 2022). "Dyslipidemia was managed pharmacologically with statin, preferably rosuvastatin, eventually combined with ezetimibe, considering the recommendation to use statins not metabolized by CYP3A4." (PMID 41440228, 2025).
liver dysfunction (15 papers, 2012 to 2025). "Hepatopathy can predispose CF patients to systemic effects as elimination is impaired by a decline of CYP3A4 enzyme functions." (PMID 23056987, 2012). "Dose adjustment is only recommended in the data sheet when co-administered with inhibitors or inducers of CYP3A4, with liver dysfunction or RI." (PMID 35745789, 2022). "Furthermore, DOAC overdoses in renal insufficiency, less frequent pharmacokinetic DDIs and contraindications with potent cytochrome P450 system 3A4 (CYP3A4) or p-glycoprotein (p-GP) inhibitors or liver dysfunction required adjustments." (PMID 39770429, 2024). "In future investigations, the exploration of polymorphism in some enzymes such as CYP3A4 and UGT1A9 may be useful to predict the sorafnib-induced liver dysfunction." (PMID 26943680, 2016). "Additionally, those with liver dysfunction, concomitant use of a strong CYP3A4 inhibitor, or of Asian race may require a lower initiation dosage because of observed increases in osilodrostat exposure and bioavailability in these populations." (PMID 40620482, 2025). "Velpatasvir is metabolized via this enzymatic pathway (also via CYP2C8 and CYP3A4), and its pharmacokinetics was not affected by liver dysfunction, which supports the proteomic findings of the present study." (PMID 36901973, 2023). "In 4 patients the planned HREZ or HRE regimen was changed to X-based regimen due to drug eruption (n = 1), drug eruption and liver dysfunction (n = 1), thrombocytopenia (n = 1), and preventing the drug interaction between Paclitaxel and RFP via CYP3A4 and CYP2C8 (n = 1)." (PMID 30314434, 2018). "The pharmacokinetic information about simeprevir, a CYP2C19 substrate (also a substrate of CYP3A4 and CYP2C8) in liver dysfunction patients is not equivocal." (PMID 36901973, 2023).